BCL2 (BCL2 apoptosis regulator)
Diseases named in the same sentence as BCL2 in open-access papers (continued):
Sharing a sentence is not in itself a finding about the gene and the disease.
cancer (continued). "Previous studies suggested that NDRG1 could inhibit proliferation and induce apoptosis of cancer cells by regulating Bcl-2 and Ca2+-associated proteins and epithelial–mesenchymal transition (EMT)." (PMID 35795037, 2022). "Bcl-2 up-regulation and Bax down-regulation have both been linked to cancer resistance." (PMID 36309655, 2022). "Resistance to apoptosis caused by large levels of the anti-apoptotic oncoprotein BCL2 may improve cancer cell survival and represent a druggable target." (PMID 35328487, 2022). "In view of the extensive association of Bcl-2 protein with cancer resistance to chemotherapeutics, this strategy may be universally applicable for overcoming the ubiquitous drug resistance to metallodrugs." (PMID 34163720, 2021). "Additionally, CSO can cause apoptosis in cancer cells by activating caspase-3, up-regulating Bax, and down-regulating Bcl-2." (PMID 34829119, 2021). "Specifically, BCL-2/BCL-XL up-regulation is clearly associated with a poor prognosis in cancer." (PMID 34502361, 2021). "The high expression of Bcl2 is usually associated with poor cell survival in many human cancers." (PMID 34400968, 2021). "The rate of apoptosis, which is often reduced in cancers, could also be due to decreased proliferation rates caused by bcl-2 (gene) on Ki-67 activities and has been related to poor survival." (PMID 34188682, 2021). "Bcl-2 is an anti-apoptotic protein that is associated with several cancer progression." (PMID 34638779, 2021). "The association of BAX -248 G>A and BCL2 -938 C>A with different cancers created conflicts." (PMID 33906310, 2021). "STAT3 is closely associated with pathogenesis of various cancers by regulating the expression of critical genes for survival, proliferation, and angiogenesis, such as Bcl-2, Bcl-xL, Mcl-1, CCND1, and VEGF, which were important for survival, proliferation, and angiogenesis." (PMID 34335938, 2021). "Altered BCL2 expression or activity has been linked to chemoresistance in a range of cancer types." (PMID 34790046, 2021). "Increased hnRNPL expression might lead to decreased degradation of the Bcl-2 mRNA, which causes cancer." (PMID 34333526, 2021). "The eponymous BCL-2 protein was identified over 30 years ago due to its association with cancer." (PMID 34515749, 2021). "Overexpression of BCL2 gene, which encodes the anti-apoptotic Bcl-2 protein, greatly contributes to the resistance of cancer cells to apoptosis, and it has also been reported to play a role in the resistance to conventional cancer treatments." (PMID 33800505, 2021). "One of pathways involved in the anti-cancer property exhibited by lycopene was associated with its ability to regulate apoptosis-related protein and gene expression such as caspase-3, caspase-8, Bax levels and Bax:Bcl-2 and Bcl-xL among cancerous cells." (PMID 34202203, 2021). "The drug-induced modulation of the Bax/Bcl-2 expression ratio (up-regulation of Bax, down-regulation of Bcl-2), associated with a release of cytochrome c and caspases activation has been clearly evidenced using colon, hepatocellular and breast cancer cells." (PMID 33534099, 2021). "Bcl2 forms a complex with Bad, leading to inhibition of Bcl2, which causes Bax and Bak1 to translocate to the mitochondria and contribute to apoptosis; however, we did not see a significant decrease in BCL2 expression in the A549 cancer stem cells." (PMID 34832951, 2021). "In addition, detection of B-cell lymphoma 2 (Bcl-2) and Bcl-2-associated X protein (Bax) can monitor the apoptosis of cancer cells." (PMID 34073054, 2021). "This ratio of Bax/Bcl-2 is linked to how sensitive or resistant cancer cells are to treatments." (PMID 31968535, 2020).
cancer (continued). "However, resistance to apoptosis is a hallmark of cancer that is achieved by disrupting the balance between pro- and anti-apoptotic Bcl2 proteins." (PMID 33027919, 2020). "Our data suggest that high concentrations of EA induce apoptosis in HER2-positive cancer cells, which might be associated with the Bcl-2/Bax/caspase-3 signaling pathway." (PMID 32947764, 2020). "Also, EGCG-induced apoptosis of cancer cells was linked with a substantial decrease in Bcl-2 and NF-κB expression." (PMID 32660101, 2020). "Furthermore, C-1305 treatment resulted in increased expression of mitochondrial apoptosis markers Bcl-2-associated X apoptosis regulator (BAX) and Bcl-2-associated agonist of cell death (BAD) in cancer cells, when compared to controls and 16HBE14o- cells." (PMID 32252403, 2020). "Bax is an antiapoptotic gene that is often under expressed in human malignancies, and it is well known for its role in cancer cell survival and resistance: it has been shown that increased Bax expression and the reduced expression of Bcl2 are important underlying mechanisms of apoptosis." (PMID 31936675, 2020). "Additionally, a significant decrease in mRNA levels of Bcl-2 was observed in cancer cells, which suggests that the loss of cell viability is connected to apoptosis." (PMID 32560101, 2020). "The clinically documented safety of glaucarubin and ABT-199 in humans highlights their potential for rapid translation towards clinical application of the dual treatment for curing other cancers with high BCL-2 levels and low mutational burdens, and therefore intact intrinsic apoptotic pathways." (PMID 32093022, 2020). "In addition, the ruthenium-phloretin complex was able to control cell proliferation and boosted apoptotic outbursts in cancer cells associated with the increase in cellular response towards Bax while diminishing responses towards Bcl-2, NF-κB, and MMP-9." (PMID 32566099, 2020). "Moreover, cholesterol treatment inverted metformin-repressed expressions of several cancer-associated genes (e.g., Bcl-xL BCL2, Zeb1, vimentin, BMI1)." (PMID 30625181, 2019). "Bcl-2 overexpression is often associated with considerable cancer cell resistance to apoptosis." (PMID 30944696, 2019). "Accumulating evidence suggests that the ratio between pro-apoptotic and anti-apoptotic Bcl-2 proteins determines the susceptibility of cancer cells, and cell apoptosis may be induced by inhibiting Bcl-2." (PMID 31906234, 2019). "Interestingly, several well-known pathways implicated in cancer progression or apoptosis were unaffected by SK KD (such as BCL2, PARP, or many transcription factors)." (PMID 30971929, 2019). "The aim of the present study was to investigate whether the use of drug-loaded microbubbles combined with ultrasound promotes the apoptosis of cancer cells by regulating B-cell lymphoma-2 (Bcl-2) and Bcl-2-associated X protein (Bax) expression." (PMID 30578377, 2019). "Therefore, Mcl-1 downregulation by XPO1 inhibitor was insufficient to induce apoptosis in cancer cells but likely made cancer cells more susceptible to inhibitors targeting of Bcl-2 and/or Bcl-xL." (PMID 31113936, 2019). "Many studies have linked the expression of Bcl-2 to the development of cancers." (PMID 31143550, 2019). "Along with changes in expression levels, other alterations that could trigger evasion of apoptosis in cancer can be related to somatic mutations in the coding region of the BCL-2 genes and their interactors." (PMID 31825969, 2019). "The results of this study also showed that with the increased concentration of Ls, the mRNA expression of Bcl-2 and Bak were significantly decreased, and the mRNA expression of Bax and caspase-3 were remarkably increased, which suggest that Ls caused the cancer cells apoptosis." (PMID 31299960, 2019).
cancer (continued). "Downregulation of pro-apoptotic Bcl-2 proteins is functionally equivalent to overexpressing the anti-apoptotic ones, and loss of expression of pro-apoptotic proteins is seen in a range of cancers." (PMID 31681471, 2019). "Our results show that Bcl-2 positivity in FMCs is associated with a better outcome by univariate and multivariate analysis in terms of disease-free interval, overall survival and cancer-specific survival in the global cohort." (PMID 30630524, 2019). "Bcl-2 has the potential to cause cancer and encodes anti-apoptotic inner mitochondrial membrane protein, and higher Bcl-2 expression has been indicated to be related to the transition to a hormone-unresponsive state with inhibited apoptosis and enhanced proliferation." (PMID 31371698, 2019). "Cancer cells that are dependent on overexpressed Bcl-2 are thus susceptible to its inhibition." (PMID 31681471, 2019). "Additionally, several well-known pathways implicated in cancer progression or apoptosis were unaffected by SK KD (such as BCL2, PARP)." (PMID 30971929, 2019). "Over expression of BCL-2 causes resistance to anti-cancer therapy." (PMID 31592099, 2019). "Mechanistically, regulation of the release of cytochrome c from mitochondria, caspase-3 and caspase-9 mRNA and protein expression, and B-cell lymphoma 2 (Bcl-2) and Bcl-2 associated X (Bax) levels, were found to be regulated in the fisetin-treated cancer cell line (oral squamous carcinoma)." (PMID 31064104, 2019). "Hence, suppressing the expression of Bcl-2 predisposes cancer cells to increased apoptosis and cell death, as evidenced for various anticancer drugs." (PMID 29587429, 2018). "PEITC (at 5–10 μM) induces apoptosis in several cell lines by a cancer cell-specific generation of ROS that is related to mitochondrial deregulation and modulation of proteins like Bcl2, BID, BIM, and BAX, causing the release of cytochrome c into cytosol leading to apoptosis." (PMID 29618945, 2018). "If such mutations were to cause reduced MOMP as shown by us, sensitivity to cancer drugs operating through the mitochondrial pathway might be predicted to improve by adding a Bcl-2 inhibitor to the initial therapy." (PMID 29670108, 2018). "Moreover, the up-regulation of anti-apoptosis Bcl-2 family proteins including Bcl-2 (B-cell lymphoma 2) and Mcl-1 (myeloid cell leukemia 1) has been associated with anoikis resistance and highly metastasis cancer cells." (PMID 29631569, 2018). "Third, Bcl-2 inhibition, mutation or depletion could significantly sensitize the anti-cancer activity by a number of molecule-targeted agents." (PMID 29416779, 2018). "In addition, its upregulation also suppresses the apoptosis of the cancer cells by decreasing B‐cell lymphoma 2 (BCL2) and increasing BCL2‐associated X protein (BAX), and baculoviral IAP repeat containing 5 (BIRC5) transcription." (PMID 29473345, 2018). "Whether Bcl-2 promoter polymorphisms are related to cancer susceptibility and prognosis, however, the results are incompatible." (PMID 28445963, 2017). "Thus Bcl-2’s link to myosin and actin underline the importance of metastasizing cancers and reiterate the interrelatedness of the internal milieu within the human body." (PMID 29049295, 2017). "Therefore, we performed this meta-analysis regarding the relationship between Bcl-2 promoter single nucleotide polymorphisms (SNPs) and cancer susceptibility and prognosis." (PMID 28445963, 2017).
cancer (continued). "This may underlie the increased sensitivity of Bcl-2-dependent cancer cells to ABT199/venetoclax in the presence of the intracellular Ca2+ buffer, BAPTA-AM." (PMID 28516063, 2017). "This might be the first meta-analysis regarding Bcl-2 promoter polymorphisms in cancer susceptibility and prognosis." (PMID 28445963, 2017). "Studies from these different cell lines and cancer cells suggest that cisplatin-induced DNA damage results in AKT phosphorylation of the pro-apoptotic factor Bcl2-associated agonist of cell death (BAD) at Ser136 to suppress cell death and promote cell survival." (PMID 28572758, 2017). "However, previous studies on the association of Bcl-2 promoter polymorphisms with predisposition to different cancer types are somewhat contradictory." (PMID 28445963, 2017). "Bcl-2 overexpression has been implicated in different carcinomas." (PMID 28197098, 2017). "For loss of Bcl-2, triple-negative BC were frequently associated with overexpression of cathepsin-D, and with aggressive disease course through lymph node invasion and high cancer cell proliferation/Ki-67 index." (PMID 27538498, 2016). "Similarly, icariside II has been shown to increase the ratio of Bax/Bcl2, causing transposition of cytochrome c and activation of caspase-3 and -9 in cancer cells including lung cancer cells and acute myeloid leukemia cells." (PMID 27445824, 2016). "In addition, the CMPTR-treated MCF-7 cancer cells were associated with decreased expression of anti-apoptotic Bcl-2 protein and increased expression of Bax/Bcl-2 ratio." (PMID 27447602, 2016). "Importantly, Bcl-2 and other anti-apoptotic proteins reported overexpressed in several cancers are associated with the development of resistance to anticancer agents, highlighting the therapeutic potential of targeting Bcl-2 in cancer treatment." (PMID 26824186, 2016). "Moreover, we found downregulation of cancer-associated genes such as BCL2, FLT3LG, or PIK3r5 in cells treated with decitabine." (PMID 27658391, 2016). "Loss of Bcl-2 expression can induce apoptosis in cancer cells." (PMID 27470322, 2016). "Overexpression of Bcl-2 and related anti-apoptotic family members may lead to an increase in the apoptotic threshold of cancer cells and has been linked to chemoresistance and poor clinical outcomes." (PMID 26910910, 2016). "Interestingly, the inhibition of apoptosis that results from dysregulation of Bcl-2 protein expression has also been shown to underlie the development of drug resistance in cancer cells." (PMID 26230693, 2015). "Additionally, BCL-2 expression has been positively associated with cancer cell differentiation and inversely with disease progression." (PMID 26132559, 2015). "Multiple functional BCL-2 genetic polymorphisms, such as rs2279115, rs1801018 and rs1564483, have been identified previously and might be involved in cancer development through deregulating BCL-2 expression." (PMID 26132559, 2015). "Indeed, proteins categorized as anti-apoptotic Bcl-2 members are transcriptionally up-regulated in cancer cells and are associated with resistance to the antitumor drugs DOX, TAX, cisplatin, mitoxantrone, and etoposide." (PMID 26370907, 2015). "That is, the rs2279115 AA genotype may result in decreased BCL-2 expression, elevated apoptosis rates of cancer cells, and thus decreased risk of malignances." (PMID 26132559, 2015).
cancer (continued). "Due to rs2279115 C-to-A change could influence BCL-2 P2 promoter activity and gene expression in cancer cells, we investigated whether there is an allele-specific effect of rs2279115 SNP on BCL-2 expression in esophagus tissues." (PMID 26132559, 2015). "Inhibition of mtDNA repair by Bcl2 in association with enhanced frequency of mtDNA damage may contribute to promotion of carcinogenesis and/or progression of cancer." (PMID 26268226, 2015). "An abundant literature has shown that polyphenols can, among others, trigger apoptosis in cancer cells through the modulation of a number of key elements in cellular signal transduction pathways linked to apoptosis (caspases, bcl-2 genes) and modulate epigenetic alterations in cancer cells." (PMID 24886433, 2014). "Confirming the role of bcl-2 in various types of cancer of heterogeneous causes is difficult; therefore, further studies with larger cohorts that include other biomarkers are necessary to define the role of bcl-2." (PMID 25380690, 2014). "Odds ratios (ORs) were used to measure the association between Bcl-2 polymorphisms and cancer risk." (PMID 25430556, 2014). "Bcl-2 is one of the original cancer genes that was identified to be associated with apoptosis." (PMID 25009620, 2014). "Therefore, well-designed prospective studies including the Bcl-2 -938C>A polymorphism and cancer susceptibility or cancer prognosis with larger sample sizes are needed to validate our findings." (PMID 25430556, 2014). "The aim of the present study was to investigate whether Bcl-2 -938C>A polymorphism can influence the susceptibility of cancer and to evaluate the prognostic significance of Bcl-2 -938C>A polymorphism in cancer." (PMID 25430556, 2014). "Cancer cells with high Bcl-2 expression are less susceptible to apoptosis by cisplatin." (PMID 29147386, 2014). "This might be the first meta-analysis regarding Bcl-2 polymorphism in cancer susceptibility and prognosis significance." (PMID 25430556, 2014). "There is increasing evidence that Bcl-2 gene polymorphism may be associated with cancer susceptibility and prognosis." (PMID 25430556, 2014). "BCL2 (encoding the protein known as apoptosis regulator Bcl-2) is the most important pro-survival or anti-apoptotic factor often overexpressed in cancer and it is closely associated with chemotherapy resistance in various cancers." (PMID 24358977, 2013). "The induction of apoptosis, cell cycle arrest and a decrease in the ratios of Bcl-2/Bax protein caused by matrine may be significant matrine anti-proliferative mechanisms against cancer cells." (PMID 24137393, 2013). "Bcl-2, and Bcl-xL protein expression has been implicated in cancer and cell transformation, therefore, we hypothesized that their overexpression in transformed cells may lead to apoptosis resistance contributing to nickel-induced carcinogenesis." (PMID 23828460, 2013). "Unfortunately, the genome-wide association studies (GWAS) database used for the current study did not include apoptosis-related sequence variants (e.g., TNF-308 rs1800629, TNFSF10 rs1131532, BCL2 -936 rs2279115) previously reported in published cancer epidemiology studies." (PMID 22546513, 2012). "Bcl-2 overexpression has been implicated in cancer chemoresistance, while high levels of pro-apoptotic proteins, such as Bax, promote apoptosis and sensitize tumor cells to various anti-cancer therapies." (PMID 23251606, 2012).